IFT70A (intraflagellar transport 70A)
Description:
Required for polyglutamylation of axonemal tubulin. Plays a role in anterograde intraflagellar transport (IFT), the process by which cilia precursors are transported from the base of the cilium to the site of their incorporation at the tip.
Synonyms: TTC30A; FLJ13946; FAP259; CFAP259; TTC30B
Tractability: PROTAC: ubiquitination databases record sites on it.
Gene: Protein-coding gene on chromosome 2 (177,612,999 to 177,618,742, reverse strand). Ensembl gene ENSG00000197557.
Subcellular location: Cell projection, cilium
Subcellular location (Human Protein Atlas): Basal body; Centrosome; Primary cilium; Nucleoplasm; Primary cilium tip
Pathways (Reactome):
Organelle biogenesis and maintenance: Intraflagellar transport
Gene Ontology:
Molecular function: intraciliary transport particle B binding
Biological process: intraciliary transport
Cellular component: axonemal microtubule; intraciliary transport particle B; cilium; intraciliary transport particle
Genetic constraint (gnomAD): Loss-of-function variants: 31 observed, 36.94 expected, observed/expected ratio (o/e) 0.84, 90% interval 0.63 to 1.13. The upper end of that interval is the gene's LOEUF score, 1.13, which puts it in group 4 of 6, group 1 being the genes least tolerant of losing a copy. Missense variants: 585 observed, 655.18 expected, observed/expected ratio (o/e) 0.89, 90% interval 0.83 to 0.96. Synonymous variants: 263 observed, 268.74 expected, observed/expected ratio (o/e) 0.98, 90% interval 0.88 to 1.08.
Homologues: Orthologues: chimpanzee IFT70A (99% identical), macaque IFT70A (99% identical), dog TTC30A (93% identical), mouse Ift70a2 (91% identical), mouse Ift70b (91% identical), mouse Ift70a1 (90% identical), tropical clawed frog ift70a (79% identical), zebrafish ift70 (75% identical), rat Ift70a2 (74% identical), Caenorhabditis elegans dyf-1 (47% identical), Drosophila melanogaster Ttc30 (46% identical). Paralogues in human: IFT70B (95% identical).
Diseases named in the same sentence as IFT70A in open-access papers:
IFT70A is named in the same sentence as 6 diseases in open-access papers, as found by Europe PMC text mining. Sharing a sentence is not in itself a finding about the gene and the disease.
IFT70A shares sentences with these, for which no sentence is quoted: polycystic kidney disease (2 papers); carcinoid tumor (1); hyperopia (1); ovarian germ cell cancer (1); synpolydactyly (1); tumor (1).